BCL6 (BCL6 transcription repressor)
Diseases named in the same sentence as BCL6 in open-access papers (continued):
Sharing a sentence is not in itself a finding about the gene and the disease.
steatosis (3 papers, 2019 to 2025). Increased lipid within the cytoplasm of cells. "Our results suggest a potential role of Bcl6 in supporting an enhanced thermogenic effect in eVAT, alleviating steatosis and associated IR in the liver, in response to EcNA intervention." (PMID 40211057, 2025). "Deletion of hepatocyte Bcl6 enhances lipid catabolism and ameliorates high-fat-diet-induced steatosis." (PMID 30983568, 2019). "Moreover, we find that ablation of hepatocyte Bcl6 increases lipid oxidation, prevents high-fat-diet-induced steatosis, and reverses fasting-related defects in Ppara-/- mice including aberrant enhancer activity, transcription, ketosis, and lipid accumulation." (PMID 30983568, 2019). "Bcl6 deletion enhances fatty acid oxidation and ameliorates steatosis." (PMID 30983568, 2019). "However, the Bcl6-LKO mice exhibited decreased degree of steatosis after short-term CDAHFD feeding." (PMID 32546802, 2020).
ulcerative colitis (3 papers, 2020 to 2025). An inflammatory bowel disease involving the mucosal surface of the large intestine and rectum. "In recent years, it has been reported that the down-regulation of Bcl6 can promote colonic epithelial cells apoptosis and M1 macrophage polarization while exacerbating the progression of ulcerative colitis (UC)." (PMID 40416976, 2025). "In conclusion, core genes (CXCL1 and BCL6) are effectiveness biomarkers for evaluating the progression from ulcerative colitis to cancer." (PMID 39582536, 2024). "They observed significant increases in BCL6 expression in the ulcerative colitis group." (PMID 39582536, 2024).
acute promyelocytic leukemia (2 papers, 2009 to 2020). An aggressive form of acute myeloid leukemia (AML), characterized by arrest of leukocyte differentiation at the promyelocyte stage, due to a specific chromosomal translocation t(15;17) in myeloid cells. "A study has reported that ZBTB16 is involved in the development of promyelocytic leukemia through interactions of the BTB-POZ domain with BCL6." (PMID 32517789, 2020).
adenomyosis (2 papers, 2020 to 2025). The growth of endometrial tissue inside the muscular wall of the uterine corpus. "Our results show that BCL6 expression is significantly higher in leiomyomas compared to adenomyosis and normal myometrium." (PMID 39903727, 2025). "Given this context and the implication of BCL6 in cell proliferation, the objective of this study is to verify BCL6 expression in cases of adenomyosis, leiomyomas, and controls (normal myometrium and endometrial glands)." (PMID 39903727, 2025). "This study investigates BCL6 expression in adenomyosis, leiomyomas, and normal myometrium using immunohistochemistry and deep learning neural networks." (PMID 39903727, 2025). "We hypothesize that BCL6 may also play a role in the pathogenesis of leiomyomas and adenomyosis." (PMID 39903727, 2025).
Alzheimer disease (2 papers, 2012 to 2025). A progressive, neurodegenerative disease characterized by loss of function and death of nerve cells in several areas of the brain leading to loss of cognitive function such as memory and language. "In Alzheimer’s disease, overexpression of BCL6 attenuates Aβ-induced neuronal damage and Tau protein hyperphosphorylation, thereby ameliorating neurodegenerative pathology." (PMID 39965013, 2025). "BCL6 has important regulatory roles in both Alzheimer’s disease and COVID-19." (PMID 39965013, 2025). "Finally, the gene ranked 5th overall, BCL6, is (together with CD24) the only immunity-related gene with significantly higher expression in severe Alzheimer’s disease that was singled out by principal component analysis (PCA)." (PMID 23066814, 2012).
brain tumor (2 papers, 2020 to 2025). "BCL6 protein was analyzed by immunofluorescence in the brain tumor, and compared to normal brain in the opposite hemisphere." (PMID 32320427, 2020).
chordoma (2 papers, 2013 to 2019). Chordomas are rare malignant tumors arising from embryonic remnants of the notochord in axial skeleton. "It was interesting to see that all chordomas showed a loss of 3q26.32 (PIK 3CA) and 3q27.3 (BCL6) thus underlining the potential importance of the PI3K pathway in chordoma development." (PMID 23533570, 2013). "For example, loss of the BCL6 locus has been reported as a possible frequent event in chordoma." (PMID 31221659, 2019).
chronic GVHD (2 papers, 2021 to 2023). "The differentiation of the PSGL1loCD4+ T helpers in chronic GVHD recipients depends on the IL-6R-Stat3-BCL6 pathway, and Stat3 or BCL6 deficiency in donor CD4+ T cells prevented expansion of the PSGL1loCD4+ T cells in GVHD target tissues." (PMID 34539630, 2021). "Prevention of PSGL1loCD4+ T expansion by BCL6 or Stat3 deficiency and by blockade of ICOS or PD-1 interaction with ICOSL or PD-L2 on B cells markedly reduced serum concentrations of autoantibodies and decreased the severity of chronic GVHD." (PMID 34539630, 2021). "In addition, we showed that GC formation is not required for induction of chronic GVHD, because recipients with an absence of BCL6 in donor B cells that could not form GCs nonetheless developed chronic GVHD." (PMID 34539630, 2021).
ductal breast carcinoma (2 papers, 2013 to 2014). "Of particular note is the observation that the relative expression of BCL-6, a proto-oncogene known to suppress genes involved in cell cycle progression, particularly cyclin D1, and inflammation, was lower in ductal carcinomas compared with pancreatitis." (PMID 23737761, 2013). "Despite the low expression of BCL-6 in ductal carcinomas, the relative expression of two BCL-6 target genes, VCAM-1 and MCP-1, was not significantly elevated in tumor samples." (PMID 23737761, 2013). "In the present studies, PPARβ/δ mRNA were increased in ductal carcinomas, while BCL-6 expression was decreased." (PMID 23737761, 2013).
gastric lymphoma (2 papers, 2016 to 2020). An extranodal lymphoma that arises from the stomach with the bulk of the mass located in the stomach. "28S rRNA has been identified as a novel fusion partner of carcinoma-related genes such as BCL6, BCL11B, IGKV3-20, and COG1 in gastric lymphoma or hematopoietic tumors." (PMID 27517048, 2016).
helminth infection (2 papers, 2013 to 2025). "Targeted deletion of BCL6 within this subset reduces the frequency of CX3CR1+CD4+ T cells during infection, underscoring the role of BCL6 in sustaining Th2 responses to helminth infections." (PMID 40634636, 2025).
hemophagocytic lymphohistiocytosis (2 papers, 2022 to 2025). "Turbinate biopsy revealed tumor cells localized predominantly within vascular lumens, positive for CD20, BCL6, PAX5, and MUM1, with a Ki-67 index >60%, confirming a diagnosis of IVLBCL with hemophagocytic lymphohistiocytosis(HLH)." (PMID 41407466, 2025).
invasive carcinoma (2 papers, 2016 to 2018). A carcinoma that is not confined to the epithelium, and has spread to the surrounding stroma. "In this study, we have demonstrated the presence of BCL6 translocation in human breast G3 stage invasive carcinoma samples as compared to G1/G2 ones." (PMID 29854311, 2018). "We found that the level of Bcl-6 was significantly higher in non-invasive carcinoma and in low- and medium-grade tumors than in invasive and high grade." (PMID 27237631, 2016).
ischemia (2 papers, 2017 to 2025). A hypoperfusion of the BLOOD through an organ or tissue caused by a PATHOLOGIC CONSTRICTION or obstruction of its BLOOD VESSELS, or an absence of BLOOD CIRCULATION. "Some of these regulators have been already associated with different forms of ischemia (e.g. Creb, Stat1, Bcl6, miR-122, miR-21, miR-214, miR-493) while others have not (e.g. Maf, Nptx1, Lef1, miR-290, miR-297, miR-466)." (PMID 29121052, 2017).
Miscarriage (2 papers, 2022 to 2024). A pregnancy that ends at a stage in which the fetus is incapable of surviving on its own, defined as the spontaneous loss of a fetus before the 22th week of pregnancy. "These genes are associated with the process of implantation and their regulation, such as BCL6, is indicative of pregnancy complications like miscarriage." (PMID 39606471, 2024). "Furthermore, this provides insights into better understanding the pathophysiology and the cellular origin associated with pregnancy complications such as implantation failure and miscarriage characterized by dysregulation of some of these gens, such as BCL6." (PMID 39606471, 2024). "In the miscarriage group, the prevalence for abnormal CD56, CD138 and BCL6 was 30%, 30% and 32%, respectively." (PMID 35040307, 2022).
nasopharyngeal carcinoma (2 papers, 2024). A carcinoma arising from the nasopharyngeal epithelium. "Moreover, the presence of the BCL6-SPECC1L fusion gene in nasopharyngeal carcinoma implies its relevance in this specific subtype." (PMID 39628997, 2024). "Thus, in nasopharyngeal carcinoma, either a reduced BCL6 expression or the presence of a BCL6-SPECC1L fusion, which removes the repressive function of the protein, has been associated with enhanced growth." (PMID 39456751, 2024).
neuropathy (2 papers, 2024 to 2025). A disorder affecting the nervous system that manifests with pain, tingling, numbness, and/or muscle weakness. "Moreover, a previous study demonstrated that the TCR repertoire overlap was observed between Tph cells and Tfh cells, and Tph cells were depleted by a Bcl6 inhibitor along with Tfh cells in the NOD.AireGW/ neuropathy murine model." (PMID 40964009, 2025).
non-alcoholic fatty liver disease (2 papers, 2019 to 2023). "Since inhibitors of BCL6 have been developed to target BCL6 and selective interactions with its corepressors, these findings also raise the possibility that BCL6 de-repression could represent a future therapeutic strategy for non-alcoholic fatty liver disease." (PMID 30983568, 2019).
osteoarthritis (2 papers, 2024). A noninflammatory degenerative joint disease occurring chiefly in older persons, characterized by degeneration of the articular cartilage, hypertrophy of bone at the margins and changes in the synovial membrane. "Firstly, the identified APDEGs—MARCKS, ZFAND5, BCL6, FOSL2, ELL2, and SGCD—may provide deeper insights into osteoarthritis pathogenesis." (PMID 39376659, 2024).
ovarian teratoma (2 papers, 2022 to 2023). A non-seminomatous germ cell tumor arising from the ovary. "Multiplex histology suggested tertiary lymphoid architectures in ovarian teratomas with dense B cell foci expressing the germinal centre marker BCL6, CD21+ follicular dendritic cells, and the NR1 subunit, alongside lymphatic vessels and high endothelial vasculature." (PMID 35680425, 2022).
ovarian tumor (2 papers, 2018 to 2020). "Moreover, depletion of BCL6 abolished the promotion of ovarian tumor progression caused by LINC00152, suggesting that the oncogenic activities of LINC00152 is a reflection of the accumulation of BCL6 protein." (PMID 33282727, 2020). "The transwell assay also demonstrated that knockdown of BCL6 partially attenuated the effects of overexpression of LINC00152 on ovarian tumor cell invasion (P < 0.05)." (PMID 33282727, 2020). "In summary, we found that LINC00152 is an applicable independent prognostic predictor of EOC, and its abnormal expression facilitates ovarian tumor proliferation and invasion by binding to Ser333/Ser343 of BCL6 to stabilizing its protein from ubiquitination." (PMID 33282727, 2020). "All these data suggest that LINC00152 prompts ovarian tumor progression in a BCL6-mediated manner." (PMID 33282727, 2020). "Furthermore, LINC00152-BCL6 interaction reinforces the oncogenic functions of BCL6 in ovarian tumor cells." (PMID 33282727, 2020). "Moreover, several invasion-related proteins such as MMP2, MMP9, and N-Cadherin have positive correlation with BCL6 in ovarian tumor cells." (PMID 30420967, 2018). "Therefore, we believe that the modification on BCL6 by LINC00152 could be a potential therapeutic target for ovarian tumor pharmacology." (PMID 33282727, 2020).
parasitemia (2 papers, 2020 to 2023). "From this, we identified 26 common DEGs downregulated in Tr1 cells from both parasitic diseases, including Ccr7, Tcf7, and Bcl6, as well as 29 upregulated DEGs, including Il10, Havcr2, Prdm1, Ccr2, Ccr5, Maf, and Lag3." (PMID 37917177, 2023). "In Plasmodium chabaudi infection, IFN-γ+ T cells control parasitemia, whereas antibody and IL-21+Bcl6+ T cells effect final clearance, suggesting an evolutionary driver for the hybrid population." (PMID 32634740, 2020).
respiratory infections (2 papers, 2021 to 2023). "The results showed that compared with children with elective surgery and respiratory infections, the HSP group had a strong tendency of higher expression of Bcl-6, while no statistical significances were shown." (PMID 34250253, 2021).
schizophrenia (2 papers, 2021 to 2023). A major psychotic disorder characterized by abnormalities in the perception or expression of reality. "Among them, the BCL6 protein level in the cerebral spinal fluid was associated with an increased risk of schizophrenia in a study, supporting the idea that Pro1338Ser mutation might contribute to the mental illness of the patient in this family." (PMID 37511534, 2023). "This suggests that in the chronic phase of schizophrenia, mRNA expressions of inflammatory mediators belonging to cluster 1 may be suppressed by the regulation of upstream transcription factors such as BCL6, RELA, and IRF9." (PMID 33815179, 2021).
serous ovarian adenocarcinoma (2 papers, 2020 to 2025). "B-cell lymphoma 6 (BCL6) is increasingly recognized as a driver of cancer progression; however, the precise molecular mechanisms by which BCL6 facilitates high-grade serous ovarian cancer (HGSOC) progression remain incompletely understood." (PMID 40777995, 2025). "Clinical analyses revealed that BCL6 expression is significantly elevated in high-grade serous ovarian cancer (HGSOC) tissues compared with that in normal tissues, whereas PLAAT4 expression is reduced." (PMID 40777995, 2025).
triple-negative breast carcinoma (2 papers, 2015). An invasive breast carcinoma which is negative for expression of estrogen receptor (ER), progesterone receptor (PR), and human epidermal growth factor receptor 2 (HER2). "Indeed, recently a small molecule inhibitor targeting Bcl6 has been developed, and combining this with a Stat3 inhibitor resulted in enhanced cell killing in triple negative breast cancer cell lines." (PMID 26187947, 2015). "Importantly, triple negative breast cancer cell lines were among the most sensitive to BCL6 inhibition." (PMID 26697522, 2015). "Inhibition of BCL6 by siRNA or the peptidomimetic RI-BPI in conjunction with inhibition of STAT3 with the Jak kinase inhibitors TG101348 or nifuroxazide led to enhanced killing of triple negative breast cancer cell lines." (PMID 26697522, 2015). "Both BCL6 and STAT3 play critical roles in triple negative breast cancer, including promoting survival and EMT, through modulating largely distinct target genes." (PMID 26697522, 2015).
urinary bladder urothelial carcinoma (2 papers, 2020 to 2025). "Additionally, recent reports have indicated that BCL6 suppresses FOXO3 activity through the activation of the PI3K‒AKT signaling pathway in urinary bladder urothelial carcinoma." (PMID 40777995, 2025).
adenoma (1 paper, 2022). A neoplasm arising from the epithelium. "Histopathological analysis of lung tumors from moribund autochthonous mice revealed that the mice harboring Bcl6 floxed alleles displayed a significant decrease in the proportion of higher-grade adenomas or carcinomas." (PMID 36377663, 2022). "Strikingly, our histological analysis showed that Kras activation with heterozygous or homozygous Bcl6 loss in lung epithelium was devoid of any hyperplasia or adenomas and even retained normal histology 12 weeks after Ad-Cre administration." (PMID 36377663, 2022). "Although BCL6-deficient mice expressing oncogenic KRAS still developed lung hyperplasia or adenoma, a dramatically reduced tumor incidence was observed upon heterozygous or homozygous loss of BCL6 in the lungs." (PMID 36377663, 2022).
AIDS (1 paper, 2007). A syndrome resulting from the acquired deficiency of cellular immunity caused by the human immunodeficiency virus (HIV). "This pattern of expression of LMP-1 and Bcl-6 in 2F7 and UMCL01-101 cells is considered a hallmark for the definition of AIDS-BL and immunoblastic AIDS-DLBCL, respectively." (PMID 17324269, 2007). "Further commonality of molecular phenotype was established through the demonstration that UMCL01-101 cells express EBV-encoded proteins LMP-1 and EBNA2, but do not express Bcl-6, a pattern definitive of immunoblastic AIDS-DLBCL." (PMID 17324269, 2007). "Analysis of LMP-1 and Bcl-6 expression indicated that UMCL01-101, like LCL8664, represents immunoblastic AIDS-DLBCL." (PMID 17324269, 2007).
anal squamous cell carcinoma (1 paper, 2023). A squamous cell carcinoma (SCC) arising from the anal canal or the anal margin (perianal skin).
anaplastic astrocytoma (1 paper, 2013). "On a cautionary note, most pilocytic astrocytomas (a distinct diagnosis, but related to anaplastic astrocytoma) carry RAF1 or BRAF rearrangements; thus it is possible that the D538-MG cell line (harboring BCL6/RAF1) was actually derived from a misdiagnosed pilocytic astrocytoma." (PMID 23637631, 2013).
Anxiety (1 paper, 2025). Intense feelings of nervousness, tension, or panic often arise in response to interpersonal stresses. "Ambiguous or borderline findings—such as equivocal CD138+ plasma cell counts, variable NK cell profiles, or inconclusive BCL-6 expression—can lead to increased anxiety, confusion about prognosis, and emotional distress." (PMID 41007809, 2025).
Ataxia (1 paper, 2022). Ataxia refers to impaired coordination of voluntary muscle movement. "These cells resist apoptosis (BCL6) and can boost DNA repair via increased ATF3, which stabilizes the major DNA damage kinase ataxia telangiectasia mutated." (PMID 35196078, 2022).
B-cell acute lymphoblastic leukemia (1 paper, 2021). A neoplasm of lymphoblasts committed to the B-cell lineage, typically composed of small to medium-sized blast cells. "BCL6, a transcription repressor, plays an important role of initiation and maintenance of germinal center reactions, which has been identified as one of predictors of outcome in several cancers, such as DLBCL and B-cell acute lymphoblastic leukemia (B-ALL)." (PMID 33629212, 2021).
bone sarcoma (1 paper, 2019). A sarcoma that arises from the bone. "Ccnb3 is a gene that has been associated with a subtype of bone sarcoma in which tumors containing a fusion between the BCL6 co-repressor (Bcor) gene and Ccnb3 gene have been shown to be distinct from Ewing sarcoma." (PMID 31013298, 2019).
bronchopulmonary dysplasia (1 paper, 2024). Bronchopulmonary dysplasia is a chronic respiratory disease that results from complications related to lung injury during the treatment of infant acute respiratory distress syndrome in low-birth-weight premature infants or from abnormal lung development in older infants. "Moreover, in a mouse bronchopulmonary dysplasia model, the FX1 inhibitor was shown to worsen the pathology, which was attributed to the role of BCL6 in inhibiting inflammation." (PMID 39456751, 2024).